INS (insulin)
Diseases named in the same sentence as INS in open-access papers (continued):
Sharing a sentence is not in itself a finding about the gene and the disease.
breast cancer (continued). "Insulin itself can induce proliferation in several breast cancer cell lines." (PMID 31315653, 2019). "Leptin, like insulin, appears to be a growth factor for breast cancer cells." (PMID 31380268, 2019). "We set out to investigate the effect of statin drugs on epigenetic modifications in multiple cell lines, including hepatocellular carcinoma, breast carcinoma, leukemic macrophages, cervical adenocarcinoma, and insulin-secreting cells, as well as liver extracts from statin-treated C57B1/6J mice." (PMID 30974899, 2019). "The role of insulin in breast cancer etiology has received growing attention in recent years." (PMID 30092829, 2018). "The results suggest that breast cancer could be preceded by systemic subclinical disturbances in glucose-insulin homeostasis characterized by mild, likely asymptomatic, IEM-like biochemical changes." (PMID 30167086, 2018). "Thus, similar to what we observed in human biopsies, murine breast cancer cells, which are spatially located in close proximity to M2-like TAMs, have activated Insulin/IGF-1 receptors." (PMID 29367764, 2018). "Until now, there is no epidemiological and animal evidence that any clinically available insulin analog, nor human insulin, increases breast cancer risk." (PMID 29615978, 2018). "Diet has been cited as an important consideration when seeking to promote improved health among breast cancer survivors given the dietary effects which can be present on hormones related to breast cancer development/metastasis such as estrogen, insulin, and IGF-1." (PMID 29880779, 2018). "Indeed, not only have biomarkers like estrogen, insulin, and IGF-1 been implicated in breast cancer development/recurrence but, more recently, myokines have been observed important to breast cancer development." (PMID 29880779, 2018). "In our study, adjustment for ER status did not materially change the results and adjustment for breast cancer subtype led to slightly stronger associations of insulin with IGF1R and p-mTOR." (PMID 29486734, 2018). "Although the majority of insulin users had prescriptions of insulin over several years prior to breast cancer diagnosis (mean: 8.4 years), we cannot guarantee the sequence of events (insulin exposure and subsequent tumor promotion) because of the potential lag time in the detection of the tumor." (PMID 29486734, 2018). "Notably, both SphK isoenzymes were equally responsible for insulin-induced cell cycle progression and the proliferation of MCF-7 breast cancer cells, although SphK1 and SphK2 had different roles in mediating insulin-induced ERK1/2 and Akt activation." (PMID 29385066, 2018). "To test whether the regulation of miR-29a in breast cancer cells cultured in human insulin medium was directly related to the IGF-1R, CDC42, or p85α, we knocked down the IGF-1R, CDC42, and p85α using siRNA." (PMID 28427228, 2017). "Similar to insulin, epidemiologic studies largely demonstrate positive associations between serum IGF-1 and cancer risk and mortality, principally among colon and postmenopausal breast cancers." (PMID 28959684, 2017). "Postmenopausal overweight is associated with increased peripheral conversion of androgens to estrogens, decreased sex hormone-binding globulin, and increased insulin levels, especially among obese smokers and drinkers, and alcohol intake further increases the synthesis of androgens and estrogens." (PMID 28746163, 2017). "It is also plausible that in obese and overweight patients higher insulin levels may activate fetal insulin/IGF-1 receptors on breast cancer cells and activate cell signaling through PI3K and Ras-Raf pathways." (PMID 28978178, 2017). "Oral drugs stimulating endogenous insulin production (insulin secretagogues) may have detrimental effects on breast cancer outcomes." (PMID 27995161, 2017).
breast cancer (continued). "Considering the relationships of these glycemic phenotypes and cancer risk, the glucose metabolism-related genetic variants that are related to impaired glucose metabolic syndromes (e.g. high glucose, insulin, and HOMA-IR levels) are plausibly associated with increased risk of breast cancer and CRC." (PMID 28446149, 2017). "Therefore, reducing the plasma level of insulin through exercise can also have therapeutic effects on survivors of breast cancer." (PMID 28178355, 2017). "Insulin increased MCF-7 human breast cancer cell proliferation and migration via the ERK pathway." (PMID 28427228, 2017). "Our observation that poor prognosis tumors are unlikely to occur more often in premenopausal women using insulin, is in line with the earlier reports that insulin (analogues) do not increase the risk of breast cancer overall." (PMID 28076434, 2017). "For instance, in a small prospective cohort of women with early-stage breast cancer, women in the highest versus lowest quartile of fasting insulin had adjusted hazard ratios of 2.1 (95% CI, 1.2 to 3.6) for disease recurrence and 3.3 (95% CI, 1.5 to 7.0) for mortality." (PMID 28959684, 2017). "In the present study we show that the interplay between heparanase and insulin signaling may foster breast tumorigenesis, mechanistically linking the enzyme into the breast cancer-promoting action of metabolic disorders." (PMID 28038446, 2017). "In the present study we analyzed clinical samples of breast carcinoma derived from diabetic/non-diabetic patients, and investigated effects of heparanase on insulin signaling in breast carcinoma cell lines, as well as insulin-driven growth of breast tumor cells." (PMID 28038446, 2017). "To test this hypothesis, we first incubated ER-positive MCF-7 human breast carcinoma cells with insulin in the absence or presence of recombinant active heparanase enzyme." (PMID 28038446, 2017). "The proteome data provided in this article were acquired from MCF7 breast cancer cells stimulated with insulin, and were generated by using a 2D-SCX (strong cation exchange)/RPLC (reversed phase liquid chromatography) separation protocol followed by tandem mass spectrometry (MS) detection." (PMID 27761513, 2016). "Duration of treatment with sulfonylurea was associated with a nonsignificant increased risk of breast cancer, after adjustment for insulin and metformin use (ORper year 1.05; 95 % CI 0.99–1.13)." (PMID 25916213, 2016). "Nine (1.4%) patients were treated with insulin at breast cancer diagnosis." (PMID 27648070, 2016). "Results from a meta-analysis of observational studies have lately shown an overall increased risk of cancer in patients treated with insulin, although a nonsignificant increased risk of breast cancer (RR 1.86; 95 % CI 0.92–2.98) was reported." (PMID 25916213, 2016). "Since insulin and leptin increase the expression of Sam68, this protein may be a point of convergence for different signals involved in breast cancer growth and progression." (PMID 27415018, 2016). "Available data from in vitro experiments suggest that insulin glargine may have greater proliferative effects than human insulin in some breast cancer cell lines." (PMID 25916213, 2016). "In this line, overexpression of insulin and leptin receptor have been found in postmenopausal breast cancer and may influence prognosis and treatment response." (PMID 27415018, 2016). "Besides, MCF7 cells have been successfully used as a pathophysiological approach for insulin and leptin-related breast cancer in previous works." (PMID 27415018, 2016). "Overweight women with low insulin levels have no elevated risk of breast cancer compared with normal-weight women with low insulin levels, and women with high insulin levels have elevated risk of breast cancer irrespective of their body weight." (PMID 27942580, 2016).
breast cancer (continued). "Some might still argue that an exposure to insulin treatment for 3 or 5 years was too short for the development of breast cancer and its progression to mortality." (PMID 26171401, 2015). "There was no demonstrated relationship between breast cancer risk and the fasting serum insulin, but there were only 136 cases aged ≥51 years and no adjustment was made for hormone replacement use." (PMID 26516917, 2015). "In breast cancer, insulin and IGFs play important roles as mitogens." (PMID 25866823, 2015). "In the epidemiological studies, the risk of breast cancer mostly showed non-significant decreased associations with insulin use vs non-insulin use (drug exposure undefined)." (PMID 26242987, 2015). "Though not statistically significant, insulin use was associated with a higher risk of breast cancer mortality, with adjusted hazard ratio (95% confidence interval) of 1.339 (0.782–2.293) and 1.384 (0.806–2.375), respectively." (PMID 26171401, 2015). "In previous European studies, the link between insulin use (including human insulin and insulin glargine) and cancer (including breast cancer) risk was not conclusive." (PMID 26171401, 2015). "Based on the current epidemiological and animal data there is no compelling evidence that any clinically available insulin analogue, or human insulin increases breast cancer risk." (PMID 26242987, 2015). "In contrast, most studies that compared insulin users with NIAD users (irrespective of the type of NIAD used) showed non-significant increased associations with risk of breast cancer." (PMID 26242987, 2015). "In addition to metformin's properties to reduce glucose and insulin in the bloodstream, it has also been shown to reduce circulating androgen and estrogen levels, which have well established mitogenic effects in breast cancer." (PMID 25866793, 2015). "In addition, serum levels of insulin, C-peptide, insulin-like growth factors, and insulin-like growth factor binding proteins are predictive for breast cancer." (PMID 26171401, 2015). "First, insulin is a well-known growth factor, which may activate the proliferation of breast cancer cells through its interaction with the insulin receptor or the IGF-1 receptor and through activating the mTOR pathway." (PMID 26537234, 2015). "The promotion of tumour cell growth upon insulin exposure may differ for different breast cancer subtypes." (PMID 26242987, 2015). "The authors of this study also reported that the estimate of breast cancer risk based on insulin was even higher in the subsample of women who did not use hormone replacement therapy (HR: 3.15; 95% CI 1.61–6.17)." (PMID 26305095, 2015). "This study adds to the literature suggesting a link of insulin use to breast cancer mortality." (PMID 26171401, 2015). "Prior studies from the Yee laboratory demonstrated that down-regulation of IGF-1R signaling in a variety of breast cancer cell lines increases insulin sensitivity by increasing cell surface expression of holo-IR due to a reduction in hybrid IR/IGF-1R cell surface expression." (PMID 26106366, 2015). "When exogenous insulin was added, these lesions might progress rapidly to invasive cancer and lead to mortality from breast cancer after several years of its use." (PMID 26171401, 2015). "Future studies are required to clarify whether the breast cancer mortality related to insulin use can be ascribed to insulin per se." (PMID 26171401, 2015). "Another explanation is that exercise affects other breast cancer risk–related mechanisms which are not (fully) fat-dependent, such as insulin sensitivity or the immune system and inflammation." (PMID 26330303, 2015). "These insulin analogues have been used for several decades, but recently some epidemiological studies found a correlation between the use of some of these compounds and cancer occurrence, especially breast cancer." (PMID 26187749, 2015). "Here we studied the role of insulin analogues in breast cancer development." (PMID 25848982, 2015).
breast cancer (continued). "There is no compelling evidence that any clinically available insulin analogue (Aspart, Determir, Glargine, Glulisine or Lispro), nor human insulin increases breast cancer risk." (PMID 26242987, 2015). "Mice treated with the insulin analog AspB10 develop larger mammary tumors than vehicle-dosed mice." (PMID 25699021, 2015). "Additionally, further research into the aetiology of insulin and breast cancer development is important." (PMID 26242987, 2015). "Metformin could decrease breast cancer cell growth either indirectly by reducing circulating insulin and insulin-like growth factor (IGF) or directly via activation of adenosine monophosphate-activated protein kinase (AMPK)." (PMID 25935404, 2015). "So far there is not a single very well-designed study to have investigated insulin treatment and breast cancer risk as the main outcome, with sufficient power." (PMID 26242987, 2015). "The Women’s Health Initiative study prospectively showed that elevated insulin level may predict postmenopausal breast cancer." (PMID 26537234, 2015). "Because the median duration of followup among those who died of breast cancer was 3.7 years, these patients should have been exposed to exogenous insulin for at least 6 years or 8 years, respectively, for those who had received insulin treatment for 3 or 5 years at baseline." (PMID 26171401, 2015). "Overall, it does appear that high circulating insulin concentrations in fasting non-diabetic postmenopausal women who are not taking replacement hormones are positively associated with breast cancer risk." (PMID 26516917, 2015). "In Model I, patients treated with human insulin alone without any OAD had a significantly higher risk of breast cancer (hazard ratio: 1.413, 95 % confidence interval: 1.030-1.940)." (PMID 26537234, 2015). "Metformin reduces circulating insulin levels in nondiabetic patients, which is relevant because higher insulin and C-peptide levels have been associated with poor outcomes in breast cancer patients." (PMID 25935404, 2015). "Therefore, the findings of the present study on the link between insulin use (mainly human) and breast cancer mortality cannot be readily extrapolated to insulin analogues." (PMID 26171401, 2015). "Therefore, the actual duration of insulin exposure in those who died of breast cancer in the present study should include the exposure period at baseline plus the follow-up duration before breast cancer mortality." (PMID 26171401, 2015). "Thus, we studied the effect of XMetS on insulin-stimulated proliferation in MCF-7 breast cancer cells and Saos-2 osteosarcoma cells, two cancer cells lines that are commonly used to determine the mitogenic effects of insulin analogs." (PMID 24533136, 2014). "There was no higher adjusted risk of breast cancer between higher quartiles of fasting insulin or non-fasting/fasting C-peptide levels and their lowest quartile levels." (PMID 24911052, 2014). "Consistent with low or physiologic concentrations of glucose used in the present study upon 2 h, previous research indicated that glucose and other factors related to glucose metabolism including insulin and IGFs may contribute to breast cancer development." (PMID 25506409, 2014). "Significant association of insulin therapy and breast cancer cases cannot be deduced due to the lack of substantial evidence." (PMID 23401790, 2013). "Our hypothesis was that the use of glargine has an impact on the mitogenic effect on tumor cells and so on the faster progression of breast carcinoma in comparison to other types of insulin." (PMID 24131755, 2013). "The aim of this retrospective study was to examine whether patients with DM using insulin glargine have a higher tumor stage of breast carcinoma in comparison to patients using other insulin." (PMID 24131755, 2013).
breast cancer (continued). "Our hypothesis was that the use of glargine has an impact on the higher mitogenic effect on tumor cells and consecutively on a faster progression of breast carcinoma in comparison to other types of insulin." (PMID 24131755, 2013). "We could not show that patients with DM using insulin glargine have a higher tumor stage of breast carcinoma in comparison to those using other types of insulin." (PMID 24131755, 2013). "Furthermore, they found that tumors of insulin-treated women had a lower proliferative activity of breast carcinoma than non-insulin treated ones." (PMID 24131755, 2013). "Using a hyperinsulinemic mouse model (MKR+/+) and the metastatic, c-Myc-transformed mammary carcinoma cell line Mvt1, we investigated how high systemic insulin levels would affect the progression of orthotopically inoculated primary mammary tumors to lung metastases." (PMID 22226054, 2012). "A 2009 study, which measured insulin at baseline and at 1, 3, and 6 years of followup, reported a HR of 2.22 (95% CI, 1.39–3.53) for incidence of breast cancer in postmenopausal women when comparing the highest baseline insulin concentration group to the lowest group." (PMID 22295251, 2012). "Likewise, in vitro, numerous studies have reported that breast cancer cell lines proliferate in response to insulin." (PMID 22226054, 2012). "In contrast, a 2007 case-control study examining blood samples in predominantly premenopausal women reported that increased levels of insulin and C-peptide were not risk factors for breast cancer." (PMID 22295251, 2012). "Therapies to reduce insulin levels in hyperinsulinemic patients suffering from breast cancer could lessen the likelihood of metastatic progression." (PMID 22226054, 2012). "Regarding the distance migrated over 10 h, MDA-MB-468 breast cancer cells appear to be more susceptible to glucose- and insulin-stimulation than SW480 colon cancer cells (p < 0.05 for 11 mM glucose, p < 0.001 for 11 mM glucose plus insulin)." (PMID 22554284, 2012). "The fact that increased breast cancer was also reported among insulin users, compared to other cancer types, suggests that such differences may be due to confounding factors rather than to the effects of medications." (PMID 22917080, 2012). "In particular, upregulation of insulin has been hypothesized to directly increase proliferation of breast tissue and breast cancer cells." (PMID 22295251, 2012). "Hormonal factors influencing the natural history of breast cancer (e.g., insulin, IGF-1, estradiol) could have effects in very short amounts of time." (PMID 22203527, 2011). "Beside its stimulating effects on breast cancer cell proliferation, insulin may influence adipokine production from adipose tissue and adipocyte stromal cells and may indirectly reinforce cancer cell growth." (PMID 21774820, 2011). "Beside its mitogenic effects, insulin may influence adipokine production from adipocyte stromal cells and paracrine enhancement of breast cancer cell growth." (PMID 21774820, 2011). "In cell culture, insulin induces a dose-dependent growth response in breast cancer cell lines acting via the insulin receptor, which has been demonstrated to be almost ubiquitously present in human breast cancer and to have prognostic significance." (PMID 24281091, 2010). "In addition, the insulin signalling pathway has been the focus of targeted therapy for breast cancer, and the purine metabolism pathway is also closely related to the pentose phosphate pathway described earlier." (PMID 21062454, 2010). "Higher levels of circulating and post-prandial insulin have been reported to enhance cellular proliferation and tumor development through upregulation of the PI3K/Akt signal pathway which is implicated in breast cancer promotion and tumorigenesis." (PMID 20148110, 2010). "We hypothesized that a diet with a reduced carbohydrate:protein ratio would have a favorable impact on breast cancer development by tempering post-prandial insulin response." (PMID 20148110, 2010).